IL1B (interleukin 1 beta)
Diseases named in the same sentence as IL1B in open-access papers (continued):
Sharing a sentence is not in itself a finding about the gene and the disease.
melanoma (continued). "For this reason, we evaluated the effect exerted by SFN and FB, administered individually or in combination, on the NLRP3 inflammasome components, as well as on the products of their activation (cleaved caspase-1 and IL-1β) in WM266-4 melanoma cells." (PMID 32486135, 2020). "In the melanoma model, the IL-1β-stimulated B16-F10 cells expressed higher levels of Nanog (P = 0.002), SOX2 (P = 0.010), and OCT4 (P < 0.001) as compared with non-stimulated cells." (PMID 32547321, 2020). "In particular, melanoma cells expressing high levels of bcl-2 displayed enhanced activation of the IL-1β/COX-2 axis, which paralleled an increased gene expression and secretion of IL-8, IL-17 and CCL2." (PMID 32269145, 2020). "Melanoma is a type of cancer that utilizes IL-1β to shape the tumor microenvironment for its own growth." (PMID 33396632, 2020). "Of note, some of these cytokines are known activators of STAT3 signaling (IL-8, IL-1β and IL-24), which is protumorigenic and favors melanoma reprogramming towards a tumor-initiating phenotype." (PMID 31906480, 2020). "ASC is involved in the inhibition of the NF-kB pathway and melanomagenesis in primary melanoma, while it activates the NF-kB pathway and supports cancer progression in metastatic melanoma through a loop of IL-1β-dependent NF-kB autoactivation." (PMID 33014808, 2020). "Taken together, these data demonstrate that IL-1β stimulation promotes the stemness capabilities of squamous carcinoma cells and melanoma cells." (PMID 32547321, 2020). "CRPs are induced in the liver by IL‐6 which is upregulated by activation of NF‐kB by IL‐1β so this is again indirect evidence for an adverse effect of activated inflammasomes on immune responses against melanoma." (PMID 32027447, 2020). "The nuclear factor-κB (NF-κB) transcription factor is involved in IL-1β mediated COX-2 expression with further PGE2 release in melanoma cells." (PMID 32296574, 2020). "A constitutive activation of the NLRP3 inflammasome in late-stage human melanoma cells with the autonomous secretion of active IL-1β has been demonstrated." (PMID 32796686, 2020). "For example, the suppression of IL-1β secretion by inhibiting inflammasome is expected to become a new treatment strategy in melanoma." (PMID 32577124, 2020). "To date, previous studies have shown that EDPs and/or VGVAPG peptide increase the production and/or secretion inflammatory markers such as IL-1α, IL-1β, and IL-6 in ligamentum flavum cells, synovial cells, and melanoma cell lines." (PMID 32463311, 2020). "We previously reported that IL-1β is spontaneously released from late-stage melanoma cells due to the constitutive activation of nuclear factor-κB (NF-κB) and NACHT, LRR and PYD domains-containing protein (NLRP) inflammasomes." (PMID 32899791, 2020). "Five molecules show a significantly (p < 0.05) different expression in melanoma vs. the controls, namely, IL-1b, IL-6, IP-10, PDGF-BB, and RANTES." (PMID 33302400, 2020). "In the B16-F10 melanoma model, the IL-1β stimulation significantly increased the percentage of ALDHhigh cells (11% vs. 4.37%)." (PMID 32547321, 2020). "Accordingly, a comparable effect was previously reported in a similar model with B16 melanoma cells, showing that tumor growth and angiogenesis was reduced in IL-1β KO mice as compared to WT mice." (PMID 33202705, 2020). "Recently, we demonstrated the involvement of NLRP1 in the acquired resistance of metastatic melanoma cells to the chemotherapy temozolomide (TMZ) by amplifying IL-1β signaling and activating nuclear factor κB (NF-κB) activity." (PMID 33396632, 2020). "The importance of IL-1β as a driver of MDSC propagation is underlined by the finding that, in peripheral blood of advanced melanoma patients, an increase in IL-1β in the serum was associated with heightened frequency of monocytic MDSCs and Treg." (PMID 32825489, 2020).
melanoma (continued). "Using B16 melanoma or 3-methylcholanthrene (3-MCA)-induced skin cancer models, it has been shown that the incidence of tumor development in mice was impaired in IL-1β-deficient or in IL-RA-treated animals." (PMID 32635472, 2020). "Inhibition of IL-1β in IL-lβ-positive melanoma cells induced cell growth arrest, which was accompanied by reduced pJNK expression." (PMID 32252279, 2020). "Elevated expression of IL-1β was observed in various human cancers, such as melanoma, colon, breast, and lung cancers." (PMID 32414062, 2020). "In this study, we observed a significant correlation (p≤ 0.05) between the DTH-PPD responses in BCG treated melanoma patients and the four gene SNPs from our panel: IL1β, NRAMP1/SLC11A1, and CXCL12." (PMID 33396862, 2020). "We showed that treatment with melanoma-derived exosomes or miR-125b-5p overexpression induced a morphological switch of M1 macrophages together with an enforced expression of IL-1β, CCL-1, CCL2, and CD80 (B7-1)." (PMID 32079286, 2020). "The inflammasome sensor, NACHT, LRR, and PYD domains-containing protein 1 (NLRP1), is responsible for IL-1β maturation and itself is a melanoma tumor promoter." (PMID 33396632, 2020). "Among the immunomodulators involved in MAFs activation, IL1β seems to be a driver of melanoma invasion both in vitro and in vivo." (PMID 33212834, 2020). "This immunocytokine delivers IL-1β activity to the tumor microenvironment and modestly slows down the subcutaneous growth of a murine B16 melanoma tumor." (PMID 33584721, 2020). "In line with this, treatment with BRAF inhibitors (BRAFi) such as dabrafenib and vemurafenib, used in melanoma patients with BRAFV600E mutation, strongly upregulated IL-1β production in myeloid mouse antigen presenting cells (APC)." (PMID 32825489, 2020). "Similar experiment in the melanoma cells also showed that cells under IL-1β stimulation possessed more stronger proliferation ability (P < 0.05)." (PMID 32547321, 2020). "IL-1β-stimulated tumor cells formed much more spheres than those in control cells in both squamous cell carcinoma (P < 0.01) and melanoma cells (P < 0.01)." (PMID 32547321, 2020). "The inhibitory effect of SFN given alone on IL-1β production is also in line with what was reported previously in different experimental models, including murine melanoma cells." (PMID 32486135, 2020). "The release of IL-1β decreased anti-tumor immune activity, thereby supporting tumor resistance to chemotherapy in murine lymphoma, melanoma and Lewis lung carcinoma." (PMID 33276524, 2020). "We next focused our attention to the melanoma models exposing bcl-2 overexpressing melanoma cells to either anti-IL-1β, anti-IL-17 or anti-IL-8 blocking antibodies and analyzing their impact on the expression of the identified bcl-2-inducible factors." (PMID 32269145, 2020). "Further, as an indirect effect, MAPKi-treated melanoma cells stimulate macrophages to produce IL-1β that in turn lead to the conversion of fibroblast into a melanoma-protective phenotype." (PMID 33212834, 2020). "In an in vivo melanoma model, IL-1β inhibition was shown to stably reduce tumour growth by limiting inflammation and inducing the maturation of immature myeloid cells into M1 macrophages." (PMID 32694701, 2020). "In another study, IL-1β was shown to increase the proportion and functionality of adoptively transferred T-cells in the tumor and to lead to the inhibition of B16 melanoma tumor growth in mice." (PMID 32635472, 2020). "Therapeutic vaccination of mice with irradiated melanoma cells that secrete IL-1β impairs tumor growth, which correlates with enhanced T cell activity (i.e. more release of IL-2/IFN-γ and augmented cytolytic activity upon ex vivo restimulation)." (PMID 33584721, 2020). "Among a dozen NLRP proteins, NLRP1 promotes melanoma by increasing IL-1β secretion and suppresses apoptosis by inhibiting CARD-containing caspase activity." (PMID 33396632, 2020).
melanoma (continued). "Most importantly, IL-1β enhanced the ability of tumor-specific T cells to trigger the regression of large, established B16 melanoma tumors in mice." (PMID 31405895, 2019). "Studies have also demonstrated a genetic association of polymorphisms in Nlrp1 gene in driving the tumorigenic process, which leads to an increase in the production of downstream mediators (i.e. CASP1 and IL-1β) in malignant melanoma." (PMID 30837326, 2019). "Late-stage human melanoma cells constitutively secrete IL-1β through spontaneous activation of the NLRP3 inflammasome, promoting inflammatory environment, macrophage chemotaxis, and angiogenesis." (PMID 31439870, 2019). "Solid tumors in which IL‐1β has been shown to be up‐regulated include breast, colon, lung, and melanomas, and patients with IL‐1β producing tumors have generally bad prognoses (Lewis, Varghese, Xu, & Alexander, 2006)." (PMID 31222982, 2019). "Solid tumors in which IL-1β has been shown to be upregulated include breast, colon, lung, head and neck cancers, and melanomas, and patients with IL-1β producing tumors generally exhibit a poorer prognosis." (PMID 31231372, 2019). "We transferred TRP-1-specific Th2 cells or classic Th9IL-4+TGF-β cells or Th9IL-4+IL-1β cells into B6 mice bearing 6-day established B16 lung metastatic murine melanoma." (PMID 30914642, 2019). "IL-1β in combination with Pmel-1 cells not only induced the regression of established B16 melanomas but also prolonged the survival of tumor-bearing mice." (PMID 31405895, 2019). "Accordingly, advanced-stage melanoma cells possess a constitutively active inflammasome cascade, possibly explaining the high levels of IL-1β found in the melanoma microenvironment." (PMID 31480312, 2019). "We found that compared with control cells, melanoma cells treated with TNFα or IL-1β displayed increased cell growth." (PMID 31015455, 2019). "Interestingly, TMEM176B was associated with diminished NLRP3 and IL1B expression in macrophages infiltrating human melanoma, suggesting that this ion channel may function as an innate checkpoint signal that hinders immune responses in the tumor microenvironment." (PMID 31085177, 2019). "Since IL-1β-mediated COX-2 mRNA expression was significantly reduced in p105-knockdown cells, it is conceivable that p105 is an important factor for translational activity in melanoma cells in response to IL-1β." (PMID 30562372, 2018). "Highly expressed IL-1β has been presented in many human cancers such as melanoma and lung, breast, colon, neck, and head cancers." (PMID 30622433, 2018). "Intravenous application of IL-1β enhanced the hepatic metastasizing ability of intrasplenically injected B16 melanoma cells." (PMID 30042333, 2018). "In melanoma cells transfected with siRNA of p65 or p105, IL-1β-mediated COX-2 mRNA expression was inhibited." (PMID 30562372, 2018). "Studies have confirmed that IL-1β, IL-1α, IL-6, IL-8, IL-18 and their receptors are permanently expressed in malignant melanoma cells, suggesting that chronic inflammation exists during the melanoma development." (PMID 30149677, 2018). "IL-1β levels were also shown to correlate with implantation and liver metastatic growth in a melanoma model." (PMID 30042333, 2018). "In a murine B16 melanoma metastasis model, intrasplenic injection of recombinant IL-1β or LPS increased experimental liver metastasis, while reduction of metastases and increased survival rates were observed following IL-1Ra treatment." (PMID 30042333, 2018). "It was also revealed, that IL-1β expression in lungs of melanoma-bearing mice is facilitated by lung-recruited mo-MDSC, resulting in enhanced E-selectin expression." (PMID 30042333, 2018). "IL-1A KO mice also displayed a reduction in melanoma growth and angiogenesis compared to WT animals, but the effect was less evident when compared to IL-1B KO mice, suggesting a major role of IL-1B." (PMID 29760166, 2018).
melanoma (continued). "On the contrary, primary melanomas at more advanced stage (> 1 mm of thickness) show up-regulation of IL-1α, IL-1β, IL-8, TNF-α, TGF-β and granulocyte-macrophage colony stimulating factor (GM-CSF)." (PMID 30591049, 2018). "We first examined the effect of the proinflammatory cytokine IL-1β on prostaglandin E2 release in canine melanoma cells." (PMID 30562372, 2018). "In line, many human tumors including advanced melanomas are characterized by high level IL-1β production due to both elevated pre IL-1β expression and enhanced Caspase-1 activity." (PMID 29983861, 2018). "Melanoma research demonstrated that the development of cancer cells was inhibited by reduced inflammasome and IL-1β expression." (PMID 30447690, 2018). "In this study, we used canine melanoma cells treated with the proinflammatory cytokine interleukin 1β (IL-1β) and investigated the transcriptional factor nuclear factor-κB (NF-κB) signaling in IL-1β-induced COX-2 expression." (PMID 30562372, 2018). "In this study, we demonstrated IL-1β-mediated COX-2 expression following prostaglandin E2 production in canine melanoma cells." (PMID 30562372, 2018). "In our investigation, the mRNA level of IL-1α, IL-1β, and IL-18 were all decreased, indicating the suppression of the inflammatory environment in human melanoma." (PMID 30149677, 2018). "Melanoma cells have also been demonstrated to spontaneously produce and release IL-1β, which leads to constitutive activation of the inflammasome." (PMID 30562372, 2018). "In this study, we also demonstrated that NF-κB p65 and p105 are involved in IL-1β-mediated COX-2 expression in melanoma cells." (PMID 30562372, 2018). "VEGF and IL-1β were demonstrated to interact in an autocrine circuit using Matrigel plugs supplemented with B16 melanoma cells." (PMID 30042333, 2018). "The expression of both IL8 and GROα in primary melanomas correlated strongly with IL1B expression, consistent with their expression being largely dependent on IL1B expression." (PMID 28450382, 2017). "IL-1β has, however, been shown to promote metastasis in a number of tumour types, such as lung cancer and melanoma." (PMID 28551814, 2017). "Fibroblasts require IL-1β to produce CXCR2 ligands, and loss of host IL-1R signaling in vivo reduces melanoma growth." (PMID 28450382, 2017). "Our data emphasize that IL-1β cannot directly induce tolerance to MAPK inhibition in melanoma cells but requires signaling through CXCR2." (PMID 28450382, 2017). "This supports the candidacy of macrophages as the primary source of IL-1β in the melanoma microenvironment, in line with our observations in melanoma biopsies." (PMID 28450382, 2017). "We have identified 4 inflammasome related Single Nucleotide Polymorphisms (SNPs) for CARD8 (rs6509365); IL1B (rs1143643) and IL18 (rs5744256 and rs1834481) related to melanoma susceptibility/protection." (PMID 27942564, 2017). "We found that NF-κB p65 phosphorylation and BCL2 expression were increased in melanoma cells treated with IL-1β–Fib-CM." (PMID 28450382, 2017). "Up-regulation of IL1B in melanoma was corroborated by microarray data analyzed through the Oncomine platform, demonstrating elevated expression in primary cutaneous melanoma compared with normal skin and benign nevi." (PMID 28450382, 2017). "Next, we analyzed how IL-1β–Fib-CM enables melanoma cells to overcome MAPK inhibition in an ERK-independent manner." (PMID 28450382, 2017). "Inhibition of NLRP3 inflammasome by thymoquinone resulted in reduced secretion of IL-1β and IL-18 with the suppressed the migration of melanoma." (PMID 28360909, 2017). "In this aspect, it has been reported that IL-1β-producing melanoma cells induce reduced tumor growth by recruiting immune cells." (PMID 28060744, 2017). "Myeloid cells are considered to be the principal producers of Il1b, although certain studies have reported il1b expression in melanoma cells and human keratinocytes." (PMID 28229859, 2017).
melanoma (continued). "Next, we performed immunohistochemical analysis to assess which cells in the melanoma microenvironment were responsible for the expression of IL-1β." (PMID 28450382, 2017). "A role for host-derived IL-1β, and to a lesser extent IL-1α, in the neovascularization and metastasis of melanoma allografts has been established using recombinant mice." (PMID 28450382, 2017). "IL-1β treatment on melanoma cells led to a significant reduction in mRNA expression of microphthalmia-associated transcription factor (MITF-M)." (PMID 28360909, 2017). "Studies in vivo showed reduced hepatic and lung metastasis of B16 melanoma cell xenografts in IL1B knockout mice." (PMID 28143606, 2017). "In contrast, early stage melanoma cells need a stimulation of IL-1R to induce the production of IL-1β." (PMID 28955343, 2017). "It is known that the NLRP3 inflammasome is constitutively activated in melanoma cells, and late-stage melanoma cells can autonomously secrete IL-1β." (PMID 27229305, 2016). "Of these, we confirmed nuclear factor kappa B (NF-κB) subunit RelA, as a novel direct target of miR-7-5p in melanoma cells, such that miR-7-5p suppresses NF-κB activity to decrease expression of canonical NF-κB target genes, including IL-1β, IL-6 and IL-8." (PMID 27203220, 2016). "In turn, this leads to reduced expression and secretion of NF-κB downstream target molecules, including IL-1β, IL-6 and IL-8, which ultimately suppresses melanoma growth and metastasis." (PMID 27203220, 2016). "In contrast, other studies revealed that inflammasomes and IL-1β contribute to melanoma and mesothelioma development." (PMID 27786298, 2016). "IL-1B expression is elevated in a variety of cancers (including breast, prostate, colon, lung, head and neck cancers and melanomas) and patients with IL-1B producing tumours generally have a worse prognosis." (PMID 27765923, 2016). "Together with our recent demonstration of ABCB5-mediated regulation of IL-1β secretion in human melanoma cells, these results suggest that the glycolysis pathway in melanoma cells is potentially regulated by an ABCB5/IL-1β/HIF-1α/PFKP signaling cascade." (PMID 27560924, 2016). "The possibility of glycolysis modulation by an ABCB5-dependent IL1β-mediated mechanism was supported by functional studies employing monoclonal antibody (mAb)-dependent ABCB5 protein inhibition in wildtype G3361 melanoma cells." (PMID 27560924, 2016). "To explore effects of IL-1β on various metastatic characteristics of melanoma cells, we examined cell viability, proliferation, adhesion ability, and colony formation of IL-1β-treated B16F10 cells." (PMID 25706411, 2015). "The elevated IL-1β correlated with higher accumulation of immunosuppressive MDSCs and formation of melanoma module in the lung of DJ-1 KO mice, and both can be decreased by treating mice with IL-1β neutralizing antibodies." (PMID 25706411, 2015). "Specifically, low A-SMase in melanoma accounts for the high expression of factors involved in inflammation (i.e., IL-1β, IL-6, GM-CSF, and TNF-α), which have been positively associated with cancer onset and progression." (PMID 26101462, 2015). "The minimal effective IL-1β concentration (0.2–2 ng/ml) to enhance proliferation, adhesion and colony formation of cultured melanoma cells was higher than the IL-1β concentration in serum (i.e. 22 pg/ml in KO and 12 pg/ml in WT mice)." (PMID 25706411, 2015). "Our results showed that IL-1β enhanced survival and colony formation of cultured melanoma cells, and that IL-1β levels were elevated both in DJ-1 KO mice and in cultured macrophage cells with DJ-1 knockdown." (PMID 25706411, 2015). "Since IL-1β has a biphasic effect on cancer metastasis when it is either insufficient or excessive, we then checked effects of IL-1β neutralization on migration of melanoma cells to lungs in both WT and DJ-1 KO mice." (PMID 25706411, 2015). "IL-1β is up-regulated in solid cancers, including breast, colon, lung, head and neck cancers, and melanomas." (PMID 26176534, 2015).